CD4 (CD4 molecule)
Diseases named in the same sentence as CD4 in open-access papers (continued):
Sharing a sentence is not in itself a finding about the gene and the disease.
infection (continued). "The host immune response to this infection is a predominantly Th2 response phenotype, where upon secondary infection, memory CD4+ T cells rapidly accumulate at the host-parasite interface and secrete IL-4, inducing localized development of alternatively activated macrophages recruited to this site." (PMID 40501701, 2025). "Infection elicited a robust pulmonary CD4+ and CD8+ T cell response." (PMID 40822581, 2025). "It has long been described that pathogenic SIV infection in macaques is also associated with increased CD4+ T cell turnover, but not in non-pathogenic infection in natural SIV hosts." (PMID 39842407, 2025). "Initially, upon SIV infection, the young RMs showed greater resilience to CD4+ T cell depletion, better control of T cell activation, hypercoagulation, and excessive inflammation, yet this resilience was progressively lost in the advanced stages of infection." (PMID 40662355, 2025). "Results from this study showed that after the challenge infection with BuAHV-1, all groups experienced a decrease in relative and absolute count of αβ T lymphocytes, starting from day 2 until day 10, mainly due to the decrease of αβT CD4+ subset." (PMID 40400665, 2025). "We have previously shown that infections by subtype C TFVs that have a higher fraction of epitopes preadapted to the HLA-directed immune response of their new host result in higher viral loads and faster CD4+ T cell decline." (PMID 40862133, 2025). "NK cells and CD4+ T cells produced comparably high levels of IFN-γ during infection as well." (PMID 39803452, 2025). "In the opposite direction, at the late stage of infection, the X4 virus has been observed to diminish immune system function by means of the activation of additional CD4+ T cells and the more efficient destruction of immune cells, thus perpetuating the inflammatory cycle and immune damage." (PMID 40709192, 2025). "CD4 is expressed at high density on the surface of CD4 T cells and at a lower density on other immune cells, such as monocytes, macrophages, and dendritic cells (DC) defining the main targets for potential infection." (PMID 41373539, 2025). "Specifically, we uniquely found that senescent T cell subtypes expressing TIGIT or TIM3 were impacted by transplantation and that TIGIT+ EM CD4 T cells, in conjunction with induction type, could predict development of infection." (PMID 40475763, 2025). "infection and CD4 cell count in HIV patients presenting with diarrhea." (PMID 40790503, 2025). "In the context of these successes and failures in curing HIV, a question emerges–are the hematopoietic stem and progenitor cells (HSPCs) themselves susceptible to infection with HIV-1 or just their differentiated progeny, e.g., macrophages, dendritic cells (DCs), and CD4+ T-cells?" (PMID 40980600, 2025). "Furthermore, TCR-dependent CD25 (IL-2Rα) expression is suggested to predict the differentiation fate of activated CD4+ T cells as early as day 3 post-infection." (PMID 40391228, 2025). "The majority of activated CD4+ T cells belonged to this cluster in third infection, and in contrast to the first infection, these cells had already increased in abundance at diagnosis; these presumably represent the stem-like memory cells identified by single-cell RNAseq." (PMID 40214640, 2025). "The Pro10, Pro20, Amo20, and Pro20 + Amo20 groups, but not the Pro40 group, showed higher proportions of CD3+ and CD3+CD4+ T cells compared with the infection group (p < 0.05), while the proportions of CD3+CD8+ T cells were increased in the Pro20 and Amo20 groups (p < 0.05)." (PMID 40305201, 2025). "Notably though, a central finding of our study was that the integration site in cells harvested from mouse grafts mirrored the integration site profile during initial infection of CD4+ T cells prior to engraftment." (PMID 41509258, 2025).
infection (continued). "They migrate from blood to sites of infection within 1–2 days of exposure, where they mount a strong inflammatory response through the production of pro-inflammatory cytokines, including TNFα and IL-6, and CD4 T-cell-recruiting chemokines CCL3-5 and CXCL8." (PMID 39861894, 2025). "CD4 T cells were more affected in terms of depletion and infection in peripheral blood." (PMID 39992151, 2025). "Additionally, DCs were found to transmit HIV to CD4 T cells via two independent mechanisms known as first-phase transfer (trans-infection) and second-phase transfer (cis-infection)." (PMID 40929143, 2025). "Likewise, in mixed bone marrow (BM) chimeric mice reconstituted with wild-type (WT) and Il2ra (CD25)−/− BM cells, infection with Listeria monocytogenes results in a reduced frequency of Th1 cells in the Il2ra−/− CD4+ T cells compared to the WT counterpart." (PMID 41000383, 2025). "Moreover, neutralizing antibodies raised against HIV-2 can potentially neutralize HIV-1 viruses preventing infection of new CD4+ T-cells and potentially slowing down HIV-1 disease progression." (PMID 40687432, 2025). "Moreover, vaccine-induced memory should aim to mimic the protective imprinting observed in natural infection with intact CD4+ T cell support as it has been pointed out before, to mitigate the risk of cross-reactive pathology upon secondary flavivirus exposure." (PMID 41295476, 2025). "For CD4+ T cells, all 15 VISORs analyzed were upregulated upon productive infection." (PMID 39798087, 2025). "Importantly, Tbet−/− mice exhibited a robust population of IL-17A producing CD4 T cells at 3 weeks post infection, confirming that Tbet prevents Th17 differentiation during Mtb infection." (PMID 40463021, 2025). "For example, in influenza A virus, vaccine strains that elicit higher T lymphocyte responses correlate with enhanced viral clearance and reduced clinical disease, while in vaccinia virus, strains that stimulate robust CD4+ lymphocyte responses provide improved protection upon virulence infection." (PMID 41446500, 2025). "The previously established role of Th2-driving epigenetic changes in neonatal CD4+ T cells, and how these may be overcome in the setting of an infection, could be explored." (PMID 40280180, 2025). "The frequency of the PD-L1-positive CD19+ B cell population remained at a high level in the established LCLs, and the frequency of the PD1-positive CD4+ T cell population also remained relatively stable until these cells disappeared approximately two weeks post-infection." (PMID 40733503, 2025). "The elevated expression of CD38 on CD4+ T-cells also is related to a poor prognosis in these subjects since it has been demonstrated that a decline important of CD4+ T-cells correspond to CD4+ CD38+ HLA-DR+ T-cell, moreover the loss of CD38+ CD4+ T-cells occurs in subjects with advanced infection." (PMID 40452022, 2025). "Others have shown that monocyte-derived macrophage (MDM) infection with T/F strains occurs more efficiently upon contact with infected CD4 T cells, but it is still unclear whether the reverse is also true (30, –, 32)." (PMID 40130873, 2025). "Infection with L4 strains resulted in significantly higher percentages of CD38-positive CD4 T cells compared to L2 Beijing strains (median scaled frequencies 0.94 vs. 0.54, respectively), while L3 strains elicited intermediate responses (median scaled frequency 0.73)." (PMID 40162896, 2025). "HIV-1 subtype A and subtype C infections have different rates of clinical disease progression, with subtype C infected individuals in the IAVI Protocol C multisite acute infection cohort having a 60% faster CD4 loss compared to subtype A." (PMID 40862133, 2025). "This was mirrored by CD4+ T cell infection rates and p24 production in cell culture supernatants." (PMID 40130873, 2025).
infection (continued). "Indeed, pretreatment of stimulated PBMC with IL1B for 2 days resulted in a dose-dependent decrease in infection with the R5-tropic YU-2 virus as determined by the frequencies of sorted p24 + CD4+ T cells." (PMID 40442100, 2025). "However, higher frequencies and cell numbers of intraepithelial Ly6A+CCR9+CD4+ T cells were infiltrated in small intestines from Trim29IEC-KO adult mice than those from Trim29fl/fl mice after EMCV infection for 3 days." (PMID 39396665, 2025). "Studies have shown racial/ethnic variation in infection acquisition and CD4 cell count as well as viral load and therefore these might reflect the WHO clinical stage for HIV infection in different populations." (PMID 41035487, 2025). "CD4+ T cells are critical for bacterial containment during S. aureus craniotomy infection." (PMID 39989461, 2025). "The fact that secondary B cell memory in vaccinated animals could be strongly boosted by natural infection suggests that secondary T cell (i.e., CD4+ and CD8+) responses, which are also critically involved in protection, were eventually also boosted." (PMID 39935478, 2025). "Further analyses were conducted to ascertain if CD4+ T cell polarization influenced by IFN-γ could be observed earlier than day 5 post-infection." (PMID 40169810, 2025). "In addition, CD4+ T cells of IAV‐only infection in the brain had a higher frequency of single‐positive CD38+ cells than the SFV‐only and coinfection groups by 10 dpi." (PMID 39971320, 2025). "Although JBNU-22-N01 infection triggered early T cell influx at 7 dpi and increased populations of effector T cells and Tregs at 14 dpi, the proportion of effector T cells remained low (< 2%) relative to the total infiltrating CD4+ and CD8+ T cells." (PMID 40459260, 2025). "Furthermore, CD4+ T cell-based therapy can improve patients’ resistance to infections significantly." (PMID 39792837, 2025). "These infections even though they are well established for their contribution in HIV transmission by penetrating protective mucosal barriers and attracting vulnerable immune cells (such as macrophages and CD4 T-helper cells) to the infection site, STIs aid in the spread of HIV." (PMID 41458404, 2025). "Yet the activation of stem-like memory CD4+ T cells in third infection coincides with the boosting (MSP-1) and diversification (AMA-1) of parasite-specific class-switched antibodies, and antiparasite immunity is dependent upon diversification (not affinity maturation)." (PMID 40214640, 2025). "Most CD4+ T cell subsets (7 out of 9) differed by infection status." (PMID 40313463, 2025). "In this clinical trial participant immune responses were predominantly seen to be mediated by CD4+ T cells, where as natural infection results in a predominant CD8+ T cell response, indicating the potential for variations between vaccine-induced immune responses and natural infection." (PMID 40756606, 2025). "However, secondary infection significantly decreased the absolute number of CD4 + IL17A + T cells in C. auris-infected mice." (PMID 40294061, 2025). "Although significant literature exists on measuring circulating effector CD4+ T cells reactive to SARS-CoV-2 proteins post-infection or vaccination, particularly through ex-vivo ELISpot, there is limited understanding of how long-term central memory CD4+ T-cell reservoirs are generated." (PMID 40303392, 2025). "Although it is unknown if MP CD4 T cells have adaptive immune functions during pathogen infection, recent studies demonstrate that about half of MP CD4 T cells express high levels of T‐bet and have innate‐like functions." (PMID 39568245, 2025). "Our results reveal a distinct biphasic pattern in EV dynamics over the course of infection, characterized by a reduction in EV release from CD4+ T cells and CD14+ monocytes during the active phase, followed by a significant resurgence during and after antimonial therapy." (PMID 40872281, 2025).
infection (continued). "Recent studies have suggested that CD4+ T cells may be target cells of infection not only in the periphery but also in the CNS during acute HIV, and may importantly contribute to establishment and maintenance of CNS HIV reservoirs." (PMID 40070827, 2025). "Our previous study demonstrating that MHC-I deficient mice developed more severe diseases than MHC-II deficient mice, which supports the hypothesis that CD8+ T cells play a more critical role than CD4+ T cells in host defense against NMI primary infection." (PMID 39469719, 2024). "Collectively, CD4 CTLs in the peripheral lymph nodes may also play a role in compensating for the immune function of the spleen to protect against infection." (PMID 38770891, 2024). "Moreover, the character of this inflammation changes over the course of untreated infection as blood CD4+ T-cells decline." (PMID 39316609, 2024). "Analyses revealed that while the percentage of CD4+ and CD8+ cells binding PNA, ALL, and MAL II remained constant through infection, a slight expression increase in the glycans recognized by these lectins was found at ten dpi, particularly within the CD4+ population." (PMID 39253089, 2024). "C57BL/6J WT and B cell, T cell, CD4+ T cell or CD8+ T cell deficient mice were IP infected with 1 × 104 GE of NMI bacteria and challenged with 1 × 107 GE of NMI bacteria at 35 days post-primary NMI-infection." (PMID 39469719, 2024). "Formation of HERV-W pseudotyped HIV allows infection of non-CD4-expressing cells." (PMID 39397863, 2024). "To incorporate the immunological mechanism of cytokines into the model, we supposed that cytokines are produced by CD4+ T cells following the initiation of infection, and lead to a time-dependent inhibition of viral production within infected SG cells, represented by f(t)." (PMID 39150988, 2024). "Additionally, we further analyzed the recovery trend of CD4 cells after infection with different subtypes in MSM and HET populations." (PMID 38994006, 2024). "Furthermore, despite the absence of a specific memory B-cell response in these individuals, SARS-CoV-2-specific memory, CD4+T-cells were discovered to endure in the peripheral blood for years after infection." (PMID 38965547, 2024). "Thus, even in the presence of infection-induced inflammation, airway CD4 Trm activation can accelerate regional T cell priming and the appearance of newly activated effector T cells in the lungs." (PMID 39688906, 2024). "Our experimental system more closely resembles the natural conditions of infection since we have studied vpr function in CD4+ T cells and in the context of replication-competent HIV, which includes the apoptotic functions previously ascribed to env, vif, nef, etc.." (PMID 39459974, 2024). "Thus, strategies to protect the CD4 T cells from new infections that can elicit a sustained CTL response in the presence of viremia are vital for achieving a functional cure against HIV." (PMID 38808136, 2024). "Compared to patients who did not have any post-operative infection, patients who developed an infection had an increase in monocyte count (p = 0.0037) and CD4+ lymphocyte IL-7R (p < 0.0001) and a decrease in monocyte CD80 (p = 0.0279) and CXCR4 expression (p = 0.0220)." (PMID 38655251, 2024). "Moreover, double positive T cells (CD4 + CD8α +) increased in the blood of chickens after infection with WT strain when compared with PBS controls (p < 0.05)." (PMID 38822378, 2024). "Notably, Rag1−/− mice that received either WT or RORγtK256R/K256R CD4+ T cells all survived and exhibited similarly low bacterial loads 20–25 days post infection, supporting effective Th17 responses against infection." (PMID 39504243, 2024). "The MPT83-specific CD4+ T cells in the lungs of immunised mice reflected the same patterns of responses seen at 4 weeks after the infection, with the CysVac5-vaccinated group being the only one with statistically significantly higher numbers of CD4+ T cells producing any cytokines." (PMID 39340027, 2024).
infection (continued). "Nutritional risk (OR=2.888) and HbA1c showed positive associations (P<0.001), while duration of HIV infection, albumin, and CD4+ T cell counts demonstrated negative associations with infection risk (P<0.05)." (PMID 39866736, 2024). "CD4+ T cells are essential for the suppression of intracellular pathogens in the early stage of infection and play critical roles in adaptive immune responses, while CD8+ T cells participate in resistance through cytolytic activity in the later stage of intracellular infection." (PMID 38932306, 2024). "In a dynamic study of an experimental infection with M. hyopneumoniae in pigs, it was found that the bacterium induced a response of CD4 (+) lymphocytes followed by an infiltration of CD8 (+) lymphocytes, in addition to mast cells, related to the pathophysiological events." (PMID 38668277, 2024). "Despite the differences in CD4 help in these model contexts in vaccinated individuals, CD4 help may be important, with CD4 persistence of up to 55 years after infection." (PMID 38932162, 2024). "This difference may be because these CD4+ T cell alterations caused by acute aortic injury are in an early stage of exhaustion progression, akin to the gradual functional decline of CD4+ T cells over time post-infection." (PMID 39266539, 2024). "In this study, we report the development and characterization of HAm, another mosaic HA antigen that contains most potential CD4+ T-cell epitopes, which promotes the humoral and cellular immune responses for broad protection and reduces viral replication immediately after infection." (PMID 39340038, 2024). "We found that the mean AUC for all the infections performed with the mutant viruses in CD4+ cells (1.37x108 pg SIV p27/106 cells) was significantly higher (p=0.0008, paired t-test) than infections in PBMC with the same mutant viruses (3.22x106 pg SIV p27/106 cells)." (PMID 39006742, 2024). "In summary, our model framework cannot recapitulate the observed associations between multiple variant infection and faster CD4+ T cell decline in the absence of an explicit dependency between the two." (PMID 39471873, 2024). "Using high-parameter flow cytometry, we evaluated these features in CD4+ T cells from rs6861(TT) versus rs6861(CC) genotyped HIV-1-infected individuals during the chronic stages of infection at steady-state and upon activation with an HIV-1 peptide-pool or soluble anti-CD3 and anti-CD28." (PMID 38548722, 2024). "CD4 T cells are known to arrive earlier than CD8 T cells at the site of infection or tissue damage." (PMID 39445067, 2024). "Thus, CD4+ T cell-secreted IL-4 and IL-5 can enhance both the primary B cell responses to vaccination and future responses to infection or vaccination." (PMID 38543915, 2024). "We hypothesize that compared to other subtypes, CRF07_BC infection might delay CD4+T lymphocyte decline and clinical progression in HIV-1 patients, potentially extending survival time and increasing transmission risks." (PMID 38994006, 2024). "This suggests that CTLA-4 expression on VZV-specific CD4 T-cells may represent a direct measure for recent antigen encounter resulting from either infection or vaccination." (PMID 39265505, 2024). "Due to the different effector immune response in the lungs of mice infected with either low or high dose of IAV, one might speculate that CD4+/CD25+FoxP3+ Tregs inhibit the T cell effector response after infection with a high dose of IAV." (PMID 38979428, 2024). "When performing a similar comparison for the models that included infection clearance by T cells, we found that the per-capita clearance rate of infected cells was a median of 3.7 times faster per virus-specific CD4+ T cell/ml than it was per virus-specific CD8+ T cell/ml in the BALF (m/n)." (PMID 39575237, 2024).